NOTCH1 (notch receptor 1)
Diseases named in the same sentence as NOTCH1 in open-access papers (continued):
Sharing a sentence is not in itself a finding about the gene and the disease.
leukemia (continued). "The IGF1-R-associated GEP further underline the biological relevance of IGF1-R in T-ALL pathogenesis as differentially up- and down-regulated genes were enriched for several known players in leukemia such as NOTCH1." (PMID 26450156, 2015). "It has been reported that Notch1 and its ligand Jagged1 are proteins with important roles in the growth of leukemia cells." (PMID 24765149, 2014). "According to this public available database, NOTCH1 is mainly overexpressed in brain cancer, gastric cancer, colorectal cancer, leukemia, and ovarian cancer." (PMID 25149541, 2014). "In this study, c-Myc abrogation depleted leukemia LICs and prolonged survival in a Notch1 mutant Tal1/Lmo2 T-ALL mouse model." (PMID 25072021, 2014). "High levels of Notch1 and Jagged1 are common in acute myeloid leukemia and chronic lymphocytic leukemia samples from patients, and leukemia cell lines." (PMID 24765149, 2014). "Functional studies of the NOTCH1 oncogene at time of overt leukemia in both human and murine LSCs showed that NOTCH1 controls leukemia initiating cell activity." (PMID 25522233, 2014). "In contrast, Notch1 and Notch2 genes were un-methylated in any of the leukemia cell lines and normal controls, while DLL1, DLL3, DLL4 and Hes6 showed only low levels of methylation (9–27%) in these leukemia cell lines." (PMID 23637910, 2013). "In the present study, we examined the expression of Notch1 and Jagged1 proteins on the surface of normal blood cells, normal bone marrow cells and various leukemia cells." (PMID 23181106, 2012). "The present study provides a flow cytometric analysis of Notch1 and Jagged1 expression in normal blood cells and various leukemia cells." (PMID 23181106, 2012). "We first examined the expression of Notch1 and Jagged1 proteins in 11 leukemia/lymphoma cell lines since we had previously detected the expression of these proteins by immunoblot analysis." (PMID 23181106, 2012). "RT-PCR in Sdl tumors demonstrated the presence of an aberrant Notch1 transcript splicing from exon 1 to exon 28 in 12 of 15 Sdl leukemias." (PMID 23133403, 2012). "The role played by Notch1 in other human leukemias is less clear, as is the potential role of other Notch genes." (PMID 22128846, 2011). "Notch1 is required for the proliferation and survival of leukemia cells, and its role has been described in recent reviews." (PMID 22128846, 2011). "In conclusion, our results may provide useful clues for developing non-invasive assays evaluating specific metabolites for diagnosis, prognosis, or metabolic-oriented therapy in NOTCH1-dependent leukemias (especially T-ALL)." (PMID 38928249, 2024). "Our preliminary results indicate that Bcat1 may be a NOTCH1 target and that Bcat1 expression increases following leukemia development." (PMID 38928249, 2024). "Knockout of ZMIZ1 inhibited the occurrence of Notch1-induced leukemia, and it was proposed that targeting ZMIZ1 could treat lymphocytic leukemia." (PMID 38866828, 2024). "Moreover, in a zebrafish model of human Notch1-induced T-ALL, stable overexpression of Bcl-2 dramatically facilitates Notch1-mediated leukemia onset, indicating the synergy between the Notch pathway and the Bcl-2-mediated anti-apoptotic pathway." (PMID 39684550, 2024). "However, NOTCH1 seems dispensable for BCP-ALL; none of the 31 leukemia cell lines studied previously expressed the NOTCH1 protein, and we were unable to detect NOTCH1 in any leukemia cell line supernatant." (PMID 37422628, 2023). "Interestingly, a recent study showed that PD-1-expressing leukemia stem cells initiate disease as those cells have high NOTCH1-MYC activity." (PMID 37108359, 2023). "On the contrary, preleukemic cells at early stages of leukemia development lacked NOTCH1 mutations and were unable to generate leukemia in secondary recipients, indicating that the acquisition of NOTCH1 mutations increases KRAS-induced T-ALL aggressiveness." (PMID 36674902, 2023).
leukemia (continued). "In conclusion, our findings uncover the oncogenic relevance of the NOTCH1 pathway in MLLr leukemia." (PMID 37833915, 2023). "The mutations of NOTCH1, PHF6 and JAK1 are closely linked in the process of leukemia, which may be the secondary genetic alterations of SET-CAN/NUP214 fusion gene." (PMID 37909026, 2023). "In summary, our data emphasize the potential relevance of the NOTCH1 pathway in MLLr leukemia." (PMID 37833915, 2023). "Moreover, IGF1R, also a NOTCH1 downstream target, is required for leukemia-initiating cell activity in T-ALL." (PMID 37833915, 2023). "It was thus predictable that deregulated NOTCH1 signaling could lead to the aberrant expansion of developing thymocytes and the generation of leukemia." (PMID 36674902, 2023). "BM cells from IGF1Rneo/neo mice transduced with NOTCH1-ΔE were able to develop leukemia, but their LIC activity was dramatically reduced compared to that of wt transduced BM cells, and T-ALL arising in first recipients was barely transplantable in secondary and tertiary hosts." (PMID 36674902, 2023). "HES1 has a central role in NOTCH1-induced leukaemia suggesting that abrogation of HES1 activity in leukemia lymphoblasts could be exploited therapeutically." (PMID 37110858, 2023). "Whether MIR139 plays a major role in NOTCH1 signaling during leukemia development remains to be investigated." (PMID 35269391, 2022). "To determine whether these leukemias were dependent on Notch1 signaling we used retroviral transduction to ectopically express a dominant negative version of the Notch1 co-activator MAML in these cells." (PMID 35371057, 2022). "ChIP-seq analysis for ICN has revealed multiple novel targets of NOTCH1 in leukemia." (PMID 35514954, 2022). "Using conditional Pten-deficient T-ALL mouse model and NOTCH1-mutated disseminated T-ALL PDX models, which recapitulate several features of human T-ALL biology, we showed that disruption of the NOTCH1-MYC-CD44 axis interferes with the maintenance of leukemia by targeting the LIC population." (PMID 35173274, 2022). "Later on, the same group revealed that T-ALL generated from fetal liver (FL) and adult BM have a dramatic difference in their T-LIC activity, i.e., that FL-derived leukemia with robust NOTCH1-driven autocrine IGF1 signaling exhibits 2-log lower T-LIC activity compared to BM-derived leukemia." (PMID 36428753, 2022). "Mutated Notch1 co-occupies the distal enhancer region of the MYC promoting activation of NFkB signaling, Hes1, PTEN, and PI3K/Akt pathways in a feed-forward loop circuit that supports leukemia cell growth, proliferation, and self-renewal." (PMID 35173274, 2022). "Leukemias arising in E2a-/- mice have mutations in the PEST domain of NOTCH1 but no mutations have been identified in the HD domain." (PMID 35514954, 2022). "NOTCH1 signaling is frequently deregulated in various types of leukemia." (PMID 35269391, 2022). "Potential E2A binding sites are also present within the alternate promoter and these alternative NOTCH1 isoforms are expressed in E2a-/- leukemias indicating that E proteins may cooperate with IKAROS to repress alternative promoter use." (PMID 35514954, 2022). "Finally, to validate the physiological relevance of the treatment combining RAP and glutamine restriction in vivo, we induced Notch1‐positive leukemia in immunodepressed mice fed with either a complete diet or with a diet without glutamine and glutamate." (PMID 33314742, 2021). "In our model, we used a glutamine/glutamate‐free diet to fed mice‐bearing Notch1‐induced leukemia." (PMID 33314742, 2021). "Finally, the combined treatment targeting mTORC1 and limiting glutamine availability had a synergistic effect to induce apoptosis and to prevent Notch1‐driven leukemia progression." (PMID 33314742, 2021). "Remarkably, Notch1 mutations that direct toward a T-ALL fate are not observed in human ETV6-RUNX1+ leukemias." (PMID 34336858, 2021).
leukemia (continued). "Thus, a glutamine‐restricted diet prevented leukemia progression specifically in mice injected with Notch1‐positive leukemic cells." (PMID 33314742, 2021). "However, earlier drug discovery attempts involving FDA-approved drug screens have resulted in the identification of leukemia-subtype specific inhibitors against for example AML1-ETO-positive acute myeloid leukemia (AML) and NOTCH1-mutated T-cell ALL." (PMID 34201500, 2021). "Moreover, we confirmed this phenotype also in vivo using mouse models, as we observed that specifically Notch1‐positive leukemia was unable to progress in mice fed with a glutamine‐free diet." (PMID 33314742, 2021). "Previous studies have shown aberrant expressions of NOTCH1 in lymphomas and leukemias." (PMID 32604737, 2020). "Inhibition of the NOTCH1 pathway in ΔE-NOTCH1 T-leukemia samples was confirmed by Western blot, showing that in DBZ- vs. DMSO-treated cells, there was a strong downregulation in ICN1 protein levels, with Dtx1, a direct target of NOTCH1, also significantly decreased." (PMID 32708470, 2020). "Consistent with this hypothesis, mice transplanted with T-cells co-expressing NOTCH1 and NRARP develop leukemia later than mice transplanted with T-NOTCH1 cells." (PMID 31586130, 2020). "Recently, miRNAs that may play critical roles in the NOTCH signaling pathway have been identified using different approaches, from genetic screens to miRNA profiling, by comparing normal T-cell subsets with NOTCH1-driven leukemia." (PMID 32708470, 2020). "Leukemia burden were reduced by 90% in animals with NOTCH1-mutant by administration of OMP-52M51." (PMID 33292596, 2020). "This is not the case for the selective PSEN1 inhibitor MRK-560, that demonstrated inhibition of mutant NOTCH1 processing and a decrease in the leukemia burden without causing gastrointestinal toxicity in T-ALL PDX in vivo." (PMID 33003595, 2020). "Similarly, inactivating gene lesions of UTX characterize a group of T-ALL patients and it has been shown that deletion of UTX accelerates leukemia growth in Notch1-dependent mice models." (PMID 31001470, 2019). "NOTCH1 signaling promotes self-renewal and survival of hematopoietic progenitor cells, and has been shown to induce c-Myc expression and to augment cell growth in leukemia." (PMID 31417884, 2019). "A 2D niche-based phenotypic screen utilizing T-ALL derived mouse leukemia stem cells co-cultured with mouse stromal cells genetically altered for optimal activation of the transmembrane receptor NOTCH1 identified compounds that were selectively toxic to stem cells of lower proliferative state." (PMID 31417884, 2019). "It was also found that the de novo acquired PTEN inactivation in Notch1-dependent leukemia could temporarily activate the PI3K/Akt signaling pathway resulting in an increase in glycolysis." (PMID 31010164, 2019). "MiR-128-3p was selected as a candidate for PHF6-targeting, which could significantly accelerate leukemia onset in a NOTCH1-induced T-ALL mouse model upon over-expression." (PMID 29435192, 2018). "All these evidences may have therapeutic implications, suggesting that an anti-NOTCH1 treatment might be able to kill not only mature CLL cells but also their corresponding leukemia stem cells, favoring disease eradication for a definitive cure." (PMID 29998084, 2018). "Given the peculiar genetic properties of our newly established cell line, we evaluated the effectiveness of several different therapeutic agents which could be effective in this model of NOTCH1-independent leukemia." (PMID 30304769, 2018).
leukemia (continued). "Altogether, this cell line may be a useful model system for dissecting the signaling pathways implicated in NOTCH1-independent T-ALL and for the screening of targeted anti-leukemia agents specific for this T-ALL subgroup." (PMID 30304769, 2018). "Importantly, inhibition of miR-193b-3p in the NOTCH1-sensitized mouse model significantly increased leukemia onset." (PMID 28270163, 2017). "The resulting leukemias were associated with c-MYC upregulation but did not develop NOTCH1 mutations." (PMID 28872614, 2017). "Finally, hairy and enhancer of split 1 homolog (HES1) which plays an important role in T-cell development and NOTCH1-induced leukemia, was recently confirmed as a critical downstream component of NOTCH1 signaling." (PMID 28872614, 2017). "The crucial importance of Notch1 in T-ALL development is underlined, as most of the mouse models showing development of leukemia due to the absence of either E2a, Ikaros, or Tcf are accompanied by activating mutations in Notch1." (PMID 27571104, 2016). "Therefore, directly targeting Notch-1 or the specific delivery of γ-secretase to Notch-positive leukemia cells is necessary to improve treatment strategies." (PMID 27233074, 2016). "The present study demonstrated that fucose-bound liposomes carrying daunorubicin could effectively target Notch-1/CD33 positive leukemia cells using the intrinsic requirement for L-fucose by such cells." (PMID 27233074, 2016). "We first analyzed the expression of CD33 and Notch-1 in various leukemia cell lines." (PMID 27233074, 2016). "Although these mutations were not the leukemia-initiating event, the likelihood of additional mutations to occur in Notch1 appears to be very high and accelerates lymphoma development." (PMID 27571104, 2016). "Cultured leukemia cells were exposed to Fuc-Liposome-daunorubicin or Liposome-daunorubicin for 2 h and then washed twice with phosphate-buffered saline to test the efficacy and specificity of daunorubicin transfer into Notch-1 positive cells." (PMID 27233074, 2016). "Furthermore, CD33 expression by leukemia cells from patients also seemed to be compatible with Notch-1 expression." (PMID 27233074, 2016). "We then investigated whether Notch-1 positive leukemia cells could be targeted by L-fucose-bound liposomes." (PMID 27233074, 2016). "Here, we show that PRDM14 binds to the Notch1 locus prior to leukemia onset." (PMID 27106930, 2016). "In addition, Notch1 signalling is intensively studied and discussed as oncogene in different tumors and as tumor suppressor in leukemias." (PMID 24740120, 2014). "Oncogenic Notch1 has well established functions in leukemia induction and leukemia maintenance." (PMID 25522233, 2014). "Interestingly, in human T-ALL patients with NOTCH1 mutations, or a transcriptional signature indicative of activated NOTCH1, GFI1 was highly expressed; while in mice, Gfi1 loss of function profoundly blocked Notch-initiated leukemia." (PMID 24068942, 2013). "Notch1 and its ligand Jagged1 are proteins with important roles in the growth of leukemia cells." (PMID 23181106, 2012). "We identified the expression of Notch1 and Jagged1 in various leukemia cells." (PMID 23181106, 2012). "While it is difficult to unravel the stepwise process of leukemia development in humans, the activating mutations in Notch1 are not always the initiating events as shown by data from a leukemia that was observed in a gene therapy trail for X-linked SCID." (PMID 23185135, 2012). "In a zebra fish model of human NOTCH1-induced T-cell leukemia, the leukemia onset was dramatically accelerated when the transgenic fish was crossed with another line over expressing the zebra fish Bcl2 gene, indicating synergy between the Notch pathway and the Bcl2-mediated antiapoptotic pathway." (PMID 23021489, 2012).
leukemia (continued). "Among the Leukemias, Notch1 deregulation is more commonly observed in T-cell Acute Lymphoblastic Leukemia which may be due to the importance of Notch signaling pathway in T cell development and proliferation of committed T-lineage progenitor cells." (PMID 24688641, 2012). "Although the translocation was later found in less than 1% of T-ALL, somatic activating mutations in Notch1 receptor were detected in over 50% of human T-ALL cases and 74% of tumors in a mouse leukemia model, showing that overexpression of activated Notch1 is indeed tumorigenic." (PMID 21637838, 2011). "Transplanted mice generate de novo clonal human leukemia that resembles T-ALL in patients, allowing for the delineation of the pathogenic events associated with the onset of the human disease, and revealing the stepwise impact of NOTCH1 mutations on human T-ALL pathogenesis." (PMID 36674902, 2023). "This is in line with other (clinical) studies showing promising results by inhibiting CXCR4 in AML or even proposing that the blockade of CDK family members, e.g., with palbociclib, could be a beneficial treatment option in combination with NOTCH1 inhibition for leukemia." (PMID 37833915, 2023). "In addition, recent studies revealed the alternative non-mutational mechanisms of NOTCH1 activation in CLL, indicating that constitutive activation of the NOTCH1 pathway in this leukemia is more frequent than previously estimated by the incidence of genetic lesions." (PMID 34442029, 2021). "Thus, the establishment of glutamine‐free diets could be considered to apply for patients bearing Notch1‐driven leukemia." (PMID 33314742, 2021). "Hence, the consequent decrement on NICD1 level causes a Notch1 on-target inhibitory effect on leukemia growth in vitro, in T-ALL xenografts, and in a Drosophila intestinal stem cell model in which Notch1 inhibition perturbs differentiation of midgut pluripotent stem cells." (PMID 33407740, 2021). "KRAS is the most common driver mutation in lung cancer, and is highly co-occurrent with KEAP1 and STK11 mutations, NOTCH1 has a putative role in skin cancer, loss of PTEN is the most common genomic alteration in glioblastoma, and DNMT3A has been associated with leukemia and myelodysplasia." (PMID 32374727, 2020). "In addition, resistant leukemias that emerged during in vivo treatment with MEK and PI3K inhibitors invariably retained multiple retroviral integrations found in the corresponding drug-sensitive parental T-ALL, but frequently showed loss of Notch1 mutation." (PMID 31199785, 2019). "Notably, the OSKM-induced apoptotic effect was also found to affect two other types of leukemia cells, i.e., MLL-NRIP3 and Notch1-induced leukemia cells, indicating a general phenomenon capable of affecting not only different types of leukemia but also various solid tumors." (PMID 31811153, 2019). "Further, aberrant expression of the NOTCH ligand, DLL4, may contribute to NOTCH1-driven leukemias." (PMID 29666622, 2018). "The genetic profile of this cell line and leukemia cases containing t(8:14)(q24;q11) leading to MYC overexpression with NOTCH1wt/FBXW7wt/PTEN mutation or deletion resembles that of a recently described Notch1-independent mouse leukemia model arising following conditional Pten deletion." (PMID 30304769, 2018). "Patient XB41 had the most homogeneous leukemia, harboring one major cluster with all mutations and two small clusters, each representing only 2% of the cells, that had acquired almost all events, except for the NKX2–1AS1–TRDC fusion and/or CMTM5 and NOTCH1 mutations." (PMID 29740158, 2018). "Finally, we evaluated the sensitivity of UP-ALL13 to therapeutic agents either currently used for the treatment of T-ALL or novel targeted therapies which could be effective in this model of NOTCH1-independent leukemia." (PMID 30304769, 2018). "Thus, aberrant expression of the NOTCH ligand delta-like 4 (DLL4) may contribute to NOTCH1-driven leukemias." (PMID 28872614, 2017).